BRCA1 (BRCA1 DNA repair associated)
Diseases named in the same sentence as BRCA1 in open-access papers (continued):
Sharing a sentence is not in itself a finding about the gene and the disease.
ovarian carcinoma (continued). "Ovarian cancers have a high frequency of homologous recombination deficiency (HRD) due to germline or somatic mutations in the BRCA1 or BRCA2 genes, methylation of the BRCA1 or RAD51C promoter regions or other genetic alterations." (PMID 32256521, 2020). "However, approximately 81% of ovarian cancers in patients with hereditary breast and ovarian cancer (HBOC) caused by BRCA1/BRCA2 gene variants are reportedly serous adenocarcinoma." (PMID 33300090, 2020). "Mutations in BRCA1 or BRCA2 are closely linked to familial breast and ovarian cancers." (PMID 31998560, 2020). "The first preclinical study evaluating PARPi veliparib in combination with anti-PD1/PD-L1 in the BRCA1-deficient BR5 mouse ovarian cancer model observed no significant boost in T cell activity and no improvement in survival." (PMID 32526888, 2020). "BRCA1 and BRCA2 gene mutations account for 10~18% of ovarian cancer." (PMID 32356124, 2020). "Since BRCTless BRCA1 isoforms are hypomorphs, abundantly expression of isoforms leads to the loss of both BRCA1 and RAD51 foci and clinically manifests as hereditary breast and ovarian cancers." (PMID 33324554, 2020). "Synthetic lethality between PARP inhibition and BRCA1/BRCA2 mutations is well-known and several PARP inhibitors, including Talazoparib, have been approved by FDA as treatments for patients with deleterious germline BRCA-mutated ovarian cancers." (PMID 33339368, 2020). "Initial studies have identified germline BRIP1 variants in BRCA1/2 mutation-negative breast and ovarian cancer patients." (PMID 32708810, 2020). "Moreover, studies that analyzed the molecular profile of BRCA1/2 in HBOC Moroccan patients rarely had ovarian cancer cases in their cohort." (PMID 32778078, 2020). "In the context of patients with known mutations in BRCA1 or BRCA2, the phase II basket study (MEDIOLA) evaluated combination of durvalumab (anti-PD-L1) and olaparib in 32 patients with platinum-sensitive relapsed ovarian cancer." (PMID 32457830, 2020). "Similarly, an international prospective study in the United States, Italy, and Spain found that ovarian cancer patients were highly satisfied with oncology clinic-based genetic testing for BRCA1 and BRCA2." (PMID 32028617, 2020). "In addition to being directly inactivated by mutation, BRCA1 and RAD51C were also found to be down-regulated through promoter hypermethylation in breast and ovarian cancer." (PMID 32029455, 2020). "We also investigated the efficacy of the combination of PARPi with ATRi or CHK1i in BRCAMUT ovarian cancer cells, as well as in serous ovarian cancers without BRCA1/2 mutation." (PMID 33352723, 2020). "However, germline variants in other genes besides BRCA1 and BRCA2 are associated with ovarian cancer predisposition, which would be missed by a genetic testing aimed only at treatment decision." (PMID 33008098, 2020). "The level of ovarian cancer risk conferred by these mutations is relatively high, indicating that after BRCA1 and BRCA2, the BRIP1, RAD51C, and RAD51D genes are the most important ovarian cancer risk genes, cumulatively contributing to ~ 2% of ovarian cancer cases." (PMID 32359370, 2020). "In addition, RNF126 can promote homologous recombination by upregulating BRCA1 expression in breast and ovarian cancers." (PMID 32131492, 2020). "Among them, niraparib was the first PARPi that have been approved for ovarian cancer without BRCA1/2 mutation." (PMID 32863940, 2020). "ChIP of endogenous or overexpressed ZC3H18 demonstrated that ZC3H18 associates with the BRCA1 promoter in multiple ovarian cancer cell lines, raising the possibility that ZC3H18 might affect the binding of transcription factors that regulate BRCA1 expression." (PMID 31604914, 2019). "It has been estimated that testing all women diagnosed with HGSC for a BRCA1 or BRCA2 gene mutation could reduce breast and ovarian cancer in first-degree relatives by 20% and 55%, respectively." (PMID 31061661, 2019).
ovarian carcinoma (continued). "Data on constitutional BRCA1 methylation with respect to ovarian cancer risk has in general been lacking." (PMID 31225507, 2019). "We then looked at the prevalence of germline BRCA1 or 2 mutations in ovarian cancer patients without any family member affected by OC or BC." (PMID 30821131, 2019). "Pathogenic variants in BRCA1 and BRCA2 cause hereditary breast and ovarian cancer." (PMID 31143303, 2019). "BRCA1-mutated (UWB1.287, SNU-251), epigenetically-silenced (OVCAR8), and wild-type (SKOV3, A2780PAR & A2780CR) ovarian cancer cell lines were exposed to clinically relevant doses of PARPi followed by different doses of standard chemotherapy and compared to the inverse treatment." (PMID 30630446, 2019). "Recently, a study in ovarian cancer also suggested that BRCA1/2 mRNA levels may be reliable biomarkers to predict responsiveness to PARPi." (PMID 30736840, 2019). "In order to simulate the situation in the BRCA1-deficient ovarian tumours carrying lower OGG1 amounts, we made use primarily of the human ovarian carcinoma cell line A2780 (ECACC 93112519), which was treated with various combinations of siRNAs and subsequently with olaparib." (PMID 31329989, 2019). "Based on a summary and analysis of 26 observational studies that included 3879 invasive epithelial ovarian cancers, the 5-year survival rates for BRCA1 mutation carriers, BRCA2 mutation carriers and noncarriers were reported as 44, 52 and 36%, respectively." (PMID 31472684, 2019). "Moreover, some authors have noted that BRCA1 and BRCA2 mutations are responsible for the development of almost 90% of all ovarian cancer cases." (PMID 30970628, 2019). "A meta-analysis study in 2014 revealed that the therapeutic efficacy of olaparib in ovarian cancer is independent of BRCA1/2 mutation status." (PMID 31102368, 2019). "Patients with BRCA1/2-associated ovarian carcinomas presented better survival results than noncarriers." (PMID 31472684, 2019). "Family history and the presence of mutations in genes such as BRCA1 and BRCA2 significantly increase the risk of development of ovarian cancer; other factors such as hormonal or reproductive factors can either increase or decrease the likelihood of this disease." (PMID 30820349, 2019). "Of the patients who tested positive for BRCA1/2 mutations, 56% had no previous family history of breast or ovarian cancer." (PMID 31061661, 2019). "BRCA1 and BRCA2 disruption is associated with hereditary breast and ovarian cancers." (PMID 31383866, 2019). "This is not ideal given that up to 44% of women with HGSC and a documented BRCA1 or BRCA2 gene mutation do not have a family history of breast/ovarian cancer." (PMID 31061661, 2019). "An assay using a loss of heterozygosity to identify genomic scarring may be useful to predict PARP inhibitor response in BRCA1/2 wild type ovarian cancers." (PMID 31374917, 2019). "We documented 2923 women with ovarian cancer (BRCA1: 2319; BRCA2: 604)." (PMID 31213659, 2019). "In Japan, three studies have clarified the frequency of germline BRCA1/2 mutation in ovarian cancer but not somatic BRCA1/2 mutation." (PMID 31780705, 2019). "To date, the exact effect of germline BRCA1/2 mutations on ovarian cancer prognosis has not yet been determined." (PMID 31064392, 2019). "In patients with ovarian cancers that are wild-type for BRCA1/2, BRCA1 promoter methylation predicted better outcome to platinum-taxane based therapy as well as PARP inhibition, as compared to patients without such methylation, thus mirroring findings in patients harbouring germline mutations." (PMID 31225507, 2019). "Women with a BRCA1 or BRCA2 mutation face elevated risks of breast and ovarian cancer." (PMID 30971774, 2019). "We applied a Mendelian randomisation approach to examine height/BMI with ovarian cancer risk using the Consortium of Investigators for the Modifiers of BRCA1/2 (CIMBA) data set, comprising 14,676 BRCA1 and 7912 BRCA2 mutation carriers, with 2923 ovarian cancer cases." (PMID 31213659, 2019).
ovarian carcinoma (continued). "Regarding the question: “In your centre, for a patient with ovarian cancer, do you request a germline or somatic BRCA1/2 as a first step?”, 19% of centers answered that the first test prescription was for somatic testing, 69% for germline, and 12% did not answer." (PMID 31600986, 2019). "Comparing the BRCA1 (A) and BRCA2 (B) carriers according to personal/family history, it was possible to see that triple negativity, bilateral breast and ovarian cancer in the proband or family were the main factors associated with the presence of a BRCA1 mutation." (PMID 31244284, 2019). "Women with a BRCA1 or BRCA2 mutation face high risks of breast and ovarian cancer." (PMID 30971774, 2019). "Several studies demonstrated that NGS could be an efficient method for detecting somatic mutations in BRCA1 and BRCA2 genes using DNA from formalin-fixed and paraffin-embedded (FFPE) breast and ovarian cancer tissues." (PMID 31065452, 2019). "BRCA mutations, in either the BRCA1 or BRCA2 gene, are also a well-known category of mutations, as women with harmful mutations in either BRCA1 or BRCA2 are known to have a risk of breast or ovarian cancer that is roughly five to 30 times the normal risk." (PMID 31610621, 2019). "The rate of germline BRCA1 or 2 mutations in ovarian cancer patients without a family history or breast or ovarian cancer is low." (PMID 30821131, 2019). "Similarly, the 9–12 del BRCA1 was identified in 9% of 92 unrelated patients with ovarian cancer of different histologies." (PMID 31545835, 2019). "The heterodimer, essential for BRCA1 stability, may be disrupted by tumorigenic mutations in BARD1 in patients with breast or ovarian cancer." (PMID 31379942, 2019). "In subnetwork 8, long-term potentiation was identified as a significant pathway, where PPP1CC and PPP1CA directly interacted with three PCOS-ovarian cancer-shared PCOSrps—i.e., BRCA1, PPP1CC, and URI1—and indirectly interacted with two shared PCOSrps (CDKN1B and SKP2)." (PMID 31216618, 2019). "In this retrospective study we evaluated clinical characteristics and BRCA1/2 genetic test results from patients with ovarian carcinoma who underwent genetic counseling at A.C.Camargo Cancer Center (Brazil) between 2015 and 2017 and had performed germline genetic testing of BRCA1/2 genes." (PMID 30606148, 2019). "In patients with ovarian cancer, 9–12 del BRCA1 was detected in 43% (13/30) of the cases." (PMID 31545835, 2019). "Given that ZC3H18 depletion caused BRCA1 promoter methylation and E2F1 recruitment to the BRCA1 promoter, we reasoned that E2F1 might repress BRCA1 expression in ovarian cancer cells by recruiting DNMT1 when ZC3H18 was depleted." (PMID 31604914, 2019). "We previously identified KJ-28d as a novel PARP inhibitor that leads to increased cytotoxicity in human ovarian cancer BRCA-1-deficient SNU-251 (BRCA1 mutation at 5564G>A) cells, as well as in triple-negative human ovarian cancer BRCA1 heterozygous (BRCA1+/−) MDA-MB-231 cells." (PMID 31795418, 2019). "In the West, it was reported that the ovarian cancer risk was higher in the BRCA1 mutation group than in the BRCA2 mutation group, while the prostate cancer risk was higher in the BRCA2 group than in the BRCA1 group." (PMID 31143373, 2019). "Of the women who tested positive for a BRCA1/2 mutation, 56% had no family history of breast or ovarian cancer." (PMID 31061661, 2019). "Germline mutations in BRCA1/2 or other HBOC-related genes are tested to determine whether the patients have a medical or family history of breast or/and ovarian cancer, with the prevalence of these mutations at ~25% in patients with breast or ovarian cancer." (PMID 31666926, 2019). "Moreover, an ATR inhibitor further enhanced the killing of BRCA1-depleted ovarian cancer cells by cisplatin, topotecan, and veliparib." (PMID 31018854, 2019).
ovarian carcinoma (continued). "Nonetheless, our current study supports previous studies suggesting that BRCA1 gene and BRCA2 gene mutations may be associated with increased susceptibilities to cancers other than breast and ovarian cancer." (PMID 30622657, 2019). "Notably, among the patients with ovarian cancer and healthy controls that we examined, BRCA1 methylation occurred independently of the two major haplotypes of the BRCA1 promoter." (PMID 31225507, 2019). "However, oestrogen, acting via the PI3K/Akt pathway in breast and ovarian cancer cells, can stimulate NRF2 in BRCA1-deficient cells and help sustain these cells which increase their genomic instability eventually leading to malignancy." (PMID 35582567, 2019). "The vast majority of individuals who carry BRCA1/2 pathogenic variant have not yet been identified, and when they are, it is often within the context of a breast and/or ovarian cancer diagnosis." (PMID 31083288, 2019). "Ovarian cancer in a personal or family history was documented in three out of seven patients who carried a pathogenic BRCA1/2 non-founder mutation." (PMID 29928469, 2018). "In the present study, we describe the development of a multiplexed, SNaPshot primer extension genotyping assay, which allows the rapid and cost-effective detection of targeted BRCA1 and BRCA2 mutations from breast and ovarian cancer patients in Chinese populations." (PMID 29487695, 2018). "A subset of these SNPs modifies the risk of breast and ovarian cancer risk for BRCA1/2 PV carriers but most of the variability has not been explained yet." (PMID 30430080, 2018). "In Brca1-deficient mouse models of ovarian cancer for example, inhibition of CTLA-4 but not PD-1/PD-L1 synergised with PARP inhibitor treatment." (PMID 29123260, 2018). "Despite International guidelines recommending testing for patients with high grade serous ovarian cancer (HGSOC) for germline BRCA1 and BRCA2 pathological variants, the uptake of genetic testing in this patient group remains low, with 19.6% of eligible patients with ovarian cancer declining test." (PMID 29344385, 2018). "Since the identification of tumor suppressor genes, BRCA1 and BRCA2, of which germline pathogenic variants predispose to a significant increase in breast and ovarian cancer risk, several other cancer-related genes have been associated with their pathogenesis and progression." (PMID 30441849, 2018). "In seven out of sixteen (44%) primary breast and ovarian cancer patients matching the criteria for BRCA1/2 testing pathogenic non-founder BRCA1/2 mutations were identified." (PMID 29928469, 2018). "In other tumor types, such as lung and ovarian cancer a high mutational burden has a survival advantage in non-ICI treated patients, but in both instances has been attributed to DNA-repair deficiency primarily via BRCA1, BRCA2, or POLE genes." (PMID 29743104, 2018). "Previous study results indicate that lack/reduction of BRCA1 expression may decrease ability in the regulation of apoptosis in breast and ovarian cancers." (PMID 29757984, 2018). "Study 19 showed a favourable final OS result irrespective of BRCA1/2 mutation status and unprecedented long-term benefit with maintenance olaparib for a subset of platinum-sensitive, recurrent ovarian cancer patients." (PMID 30353045, 2018). "Recently, Gabai-Kapara and coworkers have performed a population-based screening for ovarian cancer risk due to BRCA1 and BRCA2 in the Ashkenazi Jewish population of Israel; it was estimated that in this population 40% of ovarian cancers are due to BRCA1 and BRCA2 mutations." (PMID 29389895, 2018).
ovarian carcinoma (continued). "However, based on the age‐specific incidence rates of breast and ovarian cancer, we recommend bilateral oophorectomy at age 35 in BRCA1 carriers and at age 40 in BRCA2 carriers." (PMID 29266833, 2018). "It is important to note that almost half of patients with a BRCA1/2 mutation and ovarian cancer have no family history of breast or ovarian cancer." (PMID 29344385, 2018). "Breast and ovarian cancer risks in BRCA1/2 PV carriers might also vary according to the location of the variant and/or its origin." (PMID 30430080, 2018). "There is no international consensus up to which age women with a diagnosis of triple-negative breast cancer (TNBC) and no family history of breast or ovarian cancer should be offered genetic testing for germline BRCA1 and BRCA2 (gBRCA) mutations." (PMID 29514593, 2018). "However, nuclear expression of Maspin (mammary serine protease inhibitor), a member of the serpin superfamily and a target of truncated BRCA1, has been correlated with increased sensitivity to cisplatin with improved prognosis in ovarian cancer." (PMID 29459887, 2018). "However, in ovarian cancer BRCA1 deletions often lead to the high-CNV tandem duplicator phenotype, and this phenotype has been found to have better clinical outcome." (PMID 30061557, 2018). "All index patients met the inclusion criteria of the German Consortium for Hereditary Breast and Ovarian Cancer for germline testing and tested negative for pathogenic BRCA1/2 variants." (PMID 29368626, 2018). "The mutational profile of BRCA1/2 in families at risk for hereditary breast and ovarian cancer has not so far been reported in Andalusia (southern Spain)." (PMID 29884136, 2018). "The number of cases with ovarian cancer was too small for a valid statistical analysis (14 and 15 cases in BRCA1/2 mutation-positive and -negative group, respectively)." (PMID 29176636, 2018). "As we all know, mutations in BRCA1 and BRCA2 increase the risk of breast or ovarian cancer." (PMID 30487464, 2018). "BRCA1 and 2 dysfunction is also prevalent in sporadic epithelial ovarian cancer." (PMID 29925418, 2018). "The rate of granddaughter ovarian cancers was not different between families with and without BRCA1/2 mutations (37.3% versus 38.2%, two-sample t-test p = 0.89), therefore BRCA status cannot be a confounding variable for women ascertained for family history." (PMID 29447163, 2018). "A meta-analysis showed that BRCA2 mutation carriers did not have a significant reduction in risk of ovarian cancer while women with BRCA1 mutation did." (PMID 30174725, 2018). "Since the discovery of BRCA1, many mutations have been reported and classified which are associated with breast and ovarian cancer and cause the production of truncated and non-functional BRCA1 protein." (PMID 30283497, 2018). "The lifetime ovarian cancer risk for a woman with BRCA1 mutation is estimated to be 35% to 70%, the ovarian cancer risk lifetime for women with BRCA2 mutation is between 10 and 30%; the ovarian cancer lifetime risk for the women in the general population is less than 2%." (PMID 29389895, 2018). "Ovarian cancers were observed in 14 cases (BRCA1; 9, BRCA2; 5)." (PMID 29176636, 2018). "Importantly, five of the 13 (38.5%) BRCA1 methylation-positive ovarian cancer patients had methylated MGMT gene." (PMID 30049288, 2018). "Comprehensive and accurate analysis of BRCA1/2 genes is essential for individual and family genetic counseling in hereditary breast and ovarian cancers, as well as for establishing drug therapy with poly(ADP-ribose) (PARP) polymerases inhibitors in patients with high-grade serous ovarian cancer." (PMID 30263092, 2018). "We reported the first large-scale estimate of BRCA1/2 prevalence in Southern Chinese families, ascertained through patients with triple negative breast cancer and those that had a family history of breast and/or ovarian cancers." (PMID 29861850, 2018).